LATS1 (large tumor suppressor kinase 1)
Diseases named in the same sentence as LATS1 in open-access papers (continued):
Sharing a sentence is not in itself a finding about the gene and the disease.
ovarian carcinoma (17 papers, 2014 to 2025). A malignant neoplasm originating from the surface ovarian epithelium. "After silencing LATS1/2 in S1PR1-deficient ovarian cancer cells, senescence was suppressed and S1PR1 expression was increased concomitantly with YAP expression." (PMID 37828220, 2023). "Previous study revealed that LATS1/2 downregulation by the ubiquitin system is associated with epithelial-mesenchymal transition-like phenotypic changes in ovarian cancer cells, which trigger abnormal migration and invasion." (PMID 33062724, 2020). "Interestingly, TCGA RNASeqV2 data for serous high-grade ovarian cancer showed that both LATS1 and LATS2 expressions were associated with a higher risk for poorer survival (HR = 1.14 for LATS1 and HR = 1.08 for LATS2) for this more homogenous group of patients." (PMID 31586262, 2019). "Large tumor suppressor kinase 1 is a key component of the Hippo signaling pathway, and its down-regulation promotes epithelial–mesenchymal transition in ovarian cancer epithelial cells, resulting in enhanced invasiveness." (PMID 39253578, 2024). "Compared to cisplatin-resistant ovarian cancer cells (A2780-CP), the expression of LATS1/2 and p-YAP was increased in cisplatin-sensitive ovarian cancer cells (A2780-S), and the expression of senescence-related proteins was increased." (PMID 37828220, 2023). "Our results showed that, after S1PR1 knockdown in ovarian cancer cells, the expression of LATS1/2 was significantly increased, the level of phosphorylated YAP was increased, and the expression of PDK1 was significantly decreased." (PMID 37828220, 2023). "To further verify the role of LATS1/2 in ovarian cancer cell senescence, we silenced LATS1 and LATS2 in S1PR1 knockout ovarian cancer cells." (PMID 37828220, 2023). "LATS1 acts as a Tumor Suppressor Gene Promoter methylation targeting LATS1 inactivation in mice leads to the development of many tumors, such as ovarian cancer and sarcomas." (PMID 33773564, 2021). "We detected the level of MST1 and LATS1, which were also the important factors in the Hippo pathway, in ovarian cancer cells." (PMID 32918541, 2020). "We therefore immunohistochemically analyzed LATS expression on TMAs from a Swiss ovarian cancer cohort and compared LATS1 expression to tumor type, histology, staging, grading, and survival." (PMID 31586262, 2019). "Moreover, silencing LATS1/2 in S1PR1 knockout cells significantly decreased ovarian cancer cell senescence as per β-galactosidase staining." (PMID 37828220, 2023). "LATS1/2 silencing in S1PR1 knockout cells significantly promoted ovarian cancer cell proliferation." (PMID 37828220, 2023). "The expression of LATS1/2 was significantly increased in S1PR1-deleted ovarian cancer cells." (PMID 37828220, 2023). "For example, siRNA-induced LATS1/2 knockdown in HeLa cells and paclitaxel-sensitive ovarian cancer cells significantly attenuates cell death stimulated by paclitaxel treatment, indicating the functional role of LATS1/2 in mediating paclitaxel-induced cell apoptosis." (PMID 33467099, 2021). "Our study further confirmed that STK3 may indirectly participate in suppressing ovarian cancer by regulating the activity of LATS1/2 and YAP." (PMID 33062724, 2020). "Consistent with this hypothesis and our data, LATS1 signalization in the Hippo pathway is rendered ineffective in ovarian cancer xenograft tumors from mice treated with an Hsp90 inhibitor." (PMID 27759563, 2016).
ovarian carcinoma (continued). "They neither support the putative function of LATS proteins as tumor suppressors nor are they consistent with the previous study of ovarian cancer patients, where elevated LATS1 and LATS2 expression was associated with better outcome in serous ovarian cancer patients." (PMID 31586262, 2019). "Collectively, neither LATS1 nor LATS2 expression was associated with favorable survival in ovarian cancer and LATS2 expression may even have a negative effect on survival." (PMID 31586262, 2019). "Several interesting findings emerged from this study: Firstly, the analysis of 15 databases indicated that neither LATS1 nor LATS2 expression was associated with favorable survival in ovarian cancer and that LATS2 may even have a negative role for survival." (PMID 31586262, 2019). "In mice, ovarian cancer development is regulated through YAP, TAZ, MST1/2, SAV1, and LATS1/2 MST1/2 kinases." (PMID 39595118, 2024). "Next, we determined the expression of SIPR1, YAP, LATS1, and LATS2 in human ovarian cancer tissues using immunohistochemistry." (PMID 37828220, 2023). "In ovarian cancer cells treated with WZ10, Western blotting revealed that the expression levels of Hippo-YAP pathway-related proteins MST1/2, LATS1, p-MOB1 and p-YAP were markedly lower than in control cells." (PMID 36498794, 2022). "Here, we analyzed LATS1 and LATS2 gene expression in publicly available ovarian cancer transcriptomic data sets." (PMID 31586262, 2019). "The schematic diagram of the molecular mechanism shows that, when S1PR1 is activated by S1P or a related agonist in ovarian cancer cells, PDK1 expression is increased, LATS1/2 expression is inhibited, and YAP expression is increased, thereby inhibiting ovarian cancer cell senescence." (PMID 37828220, 2023). "Interestingly LATS1 and LATS2 proteins were higher or at least comparably expressed in ovarian cancer cell lines compared to “normal” HOSE and FT cell lines, but in no case LATS protein expression was decreased relative to the “normal” cell lines." (PMID 31586262, 2019). "Also, expression of LATS1 and LATS2 is not necessarily interdependent, meaning that high LATS1 expression does not necessarily mean high LATS2 expression in ovarian cancer cell lines." (PMID 31586262, 2019). "However, whether S1PR1 can regulate aging through PDK1 in ovarian cancer cells and whether LATS1/2 and YAP are involved in this regulation has not been reported." (PMID 37828220, 2023).
colon cancer (14 papers, 2014 to 2025). "Another study shows that the growth inhibitory effect caused by LATS1/2 deletion is due to uncontrolled activation of YAP in colon cancer." (PMID 35967587, 2022). "We detected 29 variants/SNPs within the LATS1 gene in urinary bladder and colon tumors, including 18 novel variants and 11 previously identified SNPs." (PMID 25628642, 2014). "In the current study, we investigated LATS1 genetic variations including single nucleotide polymorphisms (SNPs), in 28 Egyptian patients with either urinary bladder or colon cancers." (PMID 25628642, 2014). "Because of regional prevalence of urinary bladder and colon cancer and the latter has been previously reported to be associated with LATS1 promoter hypermethylation, we selected these particular tissues." (PMID 25628642, 2014). "However, this study reveals the significance of the tumor suppressor activity of LATS1 and highlights the association of LATS1 single-base-sequence alterations with urinary bladder and colon tumors." (PMID 25628642, 2014). "To investigate which molecules participated in 5-HT-induced signalling transduction in colon cancer cells, we first downregulated Lats1/2 expression in SW480 and SW1116 cells by introducing siRNA transfection 48 h before 5-HT stimulation." (PMID 37046308, 2023). "We believe that the STK3 and LATS1 genes among the SWH pathway factors show tumor suppressor properties in colon cancer cells since the decrease in their levels of gene expression is inter correlated." (PMID 36721804, 2023). "Primer set 5P, designed to align to exon 4 at consensus position 34481–34965 on the genomic DNA, aligned to intron 5 to intron 7 of the LATS1 gene in one of the three examined colon cancer tissues." (PMID 25628642, 2014). "This study examines the genomic LATS1 region for single-base-sequence alterations in urinary bladder and colon cancer tissues." (PMID 25628642, 2014). "This suggests that in this sample exon 4 of the LATS1 gene was shifted to a new position between intron 5 to intron 7 of the LATS1 gene in this colon cancer sample." (PMID 25628642, 2014). "We report alterations of single base pairs in the LATS1 gene, of Egyptian patients with urinary bladder and colon cancer tissues." (PMID 25628642, 2014). "Moreover, a recent study examining the effect of LATS1/2 deletion in colon cancer cell growth showed an inhibition of cell proliferation in vitro and tumor growth in vivo, together with a selective induction of WISP2 gene expression." (PMID 35326638, 2022). "Moreover, a transposition of exon 4 into another position at intron 5 to intron 7 of the LATS1 gene was observed in a colon cancer tissue." (PMID 25628642, 2014). "This transposition within the LATS1 gene alters the amino acid sequence of the Serine/Threonine catalytic domain of LATS1 protein and may result in LATS1 inactivation in colon cancer." (PMID 25628642, 2014). "Accumulating evidence supports that the LATS family of human tumor suppressors (LATS1 and LATS2) is a new governor of cell homeostasis and LATS2 is downregulated in many cancers, such as prostate cancer and colon cancer." (PMID 31316723, 2019). "Likewise, Hippo kinases LATS1 and LATS2, the immediate downstream phospho-targets of STK3/4, were also shown to be essential for tumor cell growth in a colon cancer." (PMID 37345153, 2023). "To investigate whether it was LATS1/2 kinases that affected YAP/TAZ protein levels in COAD, we first analyzed the colon cancer TCGA dataset with 275 COAD and 349 control tissues." (PMID 33414893, 2020). "Furthermore, over-expressing miR-590-3p inhibited expressions of LATS1 and SAV1, promoted YAP1 expression and didn’t effect MST1 expression in colon cancer cells." (PMID 28938537, 2017).
colon cancer (continued). "Enhancement of Hippo-YAP signaling pathway and its key components, including LATS1/2 and MST1/2, were involved in tumorigenesis, proliferation, invasion, migration, and drug resistance of multiple types of malignancies, such as lung, small intestine, breast and colon cancers." (PMID 39715773, 2024). "However, the effects elicited by the activation of HIPPO pathway under ER stress may not depend on LATS1/2 inasmuch as other kinases downstream of MST1 and 2 such as the nuclear dbf2-related (NDR) kinase have been implicated in YAP phosphorylation and inhibition of liver and colon cancer." (PMID 27409837, 2016).
soft tissue sarcoma (14 papers, 2009 to 2025). A malignant neoplasm arising from muscle tissue, adipose tissue, blood vessels, fibrous tissue, or other supportive tissues excluding the bones. "Loss of function of either LATS1 or LATS2 leads to a variety of tumor types including soft tissue sarcomas, leukemia, as well as breast, prostate, lung and esophageal cancers, which suggests they function as tumor suppressors in tumor pathogenesis." (PMID 22909338, 2012). "Notably, LATS1 is repressed in human cancers, and LATS1 mutations lead to soft tissue sarcoma formation." (PMID 39895792, 2025). "Another in vivo study showed that LATS1 knockout led to ovarian stromal cell tumors and soft tissue sarcomas in 4-month-old mice; and mice with LATS1 gene deletion showed pituitary hyperplasia." (PMID 36009693, 2022). "Previous global deletion of Lats1 in mice resulted in a variety of soft tissue sarcomas and stromal cell tumours." (PMID 30912742, 2019). "Transgenic mice with liver-specific YAP overexpression exhibit dramatically increased liver size and eventually develop tumors, while LATS1 knockout leads to soft tissue sarcoma and ovarian tumor development." (PMID 26561204, 2015). "The large tumor suppressor 1 (LATS1) is inactivated in various tumor types encompassing soft tissue sarcomas, and adenoid cystic carcinoma, as well as, breast, lung, prostate and esophageal cancers." (PMID 25628642, 2014). "Lats1- knockout mice spontaneously developed large soft tissue sarcomas and ovarian stromal cell tumors and a high sensitivity to carcinogenic treatments, suggesting that Lats1 is a tumor suppressor at least in mice." (PMID 22909338, 2012). "Lats1-deficient mice spontaneously developed non-metastatic ovarian stromal cell tumours and metastatic large soft tissue sarcomas with a penetrance of 100% and 14%, respectively." (PMID 19656388, 2009). "Moreover, Lats1 knockout mice induced the formation of ovarian tumors and soft tissue sarcomas." (PMID 25628642, 2014).
colorectal cancer (12 papers, 2016 to 2025). A primary or metastatic malignant neoplasm that affects the colon or rectum. "Loss of Lats1/2 inhibits colorectal cancer progression through YAP-mediated inhibition of Wnt signaling and intestinal stem cell activity." (PMID 35654829, 2022). "Decreased expression of LATS1 in colorectal cancer was in association with the promoter methylation." (PMID 26942001, 2016). "Similarly, while our study determined that LATS1 mutations were also associated with a survival benefit in the combined, bladder, and colorectal cancer cohorts, very little is known regarding LATS1 mutations and ICI responses." (PMID 35798829, 2022). "Notably, the phenotype of Lats1/2 dKO, or nlsYAP5SA expression, appears to be a chronic regenerative proliferation response, which we observe induces diarrhoea, strongly reminiscent of inflammatory colitis—a key factor predisposing patients to colorectal cancer." (PMID 33950519, 2021). "LATS1's biological effects on colorectal cancer (CRC) are yet to be determined." (PMID 35003351, 2021). "In colorectal carcinoma (CRC), Chen Li proved the inhibition effect of lncRNA NBAT-1 on the development of OXA-resistant CRC cells by suppressing miR-4504 to mediate the WWC3/LATS1/YAP axis." (PMID 38243168, 2024).
mesothelioma (12 papers, 2015 to 2025). A usually malignant and aggressive neoplasm of the mesothelium which is often associated with exposure to asbestos. "In 2015 the exome sequencing has revealed some mutations and fusions of MST1/2 or LATS1/2 kinases in cancer, for example LATS1 fusion in mesothelioma." (PMID 38163861, 2024). "Disruption of the YAP/TAZ–TEAD interaction by IAG933 and YTP-75 was demonstrated by coimmunoprecipitation following incubation of the Hippo-altered mesothelioma cell line MSTO-211H (LATS1/LATS2 loss of function) with IAG933 or YTP-75, an IAG933 analog with a cellular potency within a similar range." (PMID 38565920, 2024). "Additionally, our combined approach detected CNV events at other genes associated with mesothelioma: lost copies of LATS1 (associated with hippo signaling) and NF2 (a tumor suppressor) and the amplification of the YAP gene, responsible for encoding a protein that activates transcription factors." (PMID 26185765, 2015). "To identify molecular features associated with this sensitivity, we examined the mutational status of genes commonly altered in mesothelioma, including NF2, LATS1/2, and BAP1." (PMID 41463232, 2025). "Three mesothelioma cell lines were used in this assay: NCI-H2052 cells harboring NF2 mutations, Y-MESO-27 cells with LATS1/2 alterations, and NCI-H2452 cells carrying BAP1 mutations." (PMID 41463232, 2025). "A comprehensive genome analysis of mesothelioma tissues detected frequent allelic loss among several Hippo pathway gene regions such as MST1 and LATS1." (PMID 37180489, 2023). "To validate our whole-genome screens, we used CRISPR/Cas9 mutagenesis with two independent sgRNAs to mutate NF1, SOCS3, and VGLL4 in H226 and H2052 cells, as well as a third mesothelioma cell line, MSTO-211H, which harbors inactivating mutations in both LATS1 and LATS2." (PMID 39103676, 2024). "It was shown that LATS1/2 are functional targets of CRL4DCAF1 and that in tumors with mutated NF2, such as mesothelioma, activated CRL4 induces LATS1/2 ubiquitination to promote their degradation and YAP/TAZ activation, thus stimulating oncogenesis (shown in purple)." (PMID 29587439, 2018). "We found RASSF7 amplification in 39 mesotheliomas, NF2 mutations in 24, LATS2 mutations in 6 and LATS1 in 2, so that non-overlapping lesions in Hippo pathways were present in 52/121 mesotheliomas (43%) and a further 9 mesothelioma had more than one lesion (total 50%)." (PMID 34580349, 2021). "Moreover, CRL4DCAF1 was shown to directly bind to LATS1/2 and induce their ubiquitination and degradation; thus, upregulated CRL4DCAF1 in NF2-inactivated mesothelioma cells accelerates degradation of LATS1/2 and hence activates YAP." (PMID 37180489, 2023). "Collectively, our results suggest that Rho/ROCK could regulate the Hippo pathway through additional mechanisms besides LATS1/2, and that kinase inhibitors of Rho/ROCK may have therapeutic roles for mesothelioma treatment through regulation of the Hippo pathway." (PMID 28470935, 2017).
breast tumors (11 papers, 2009 to 2025). "In line with this, LATS1 has been linked to cancer cell plasticity and increased resistance to hormone therapy in breast tumors." (PMID 38565950, 2024). "For example, more than half of human breast tumors have hypermethylation at either the Lats1 or Lats2 CpG island, resulting in lower expression of Lats1/2 mRNA and an association with more aggressive tumors." (PMID 25097728, 2014). "Lats1 mRNA steady-state level was increased approximately 3-fold in Hs578T breast tumor cells that were infected with the p110 CUX1 retroviral vector." (PMID 19656388, 2009). "This analysis revealed a positive correlation between expression of the LATS1/2-KO epithelial signature and the presence of both CAF and macrophage populations in human breast tumors (Fig. EV4H)." (PMID 39953252, 2025). "Concurrently, downregulation of total endogenous levels of MST2, LATS1 and the phosphorylated forms of YAP/TAZ was observed, indicating deregulation of Hippo signaling pathway in breast tumors." (PMID 39979255, 2025). "We further show that PYK2 enhances the tyrosine phosphorylation of both TAZ and LATS1/2 and concomitantly TAZ stability, and that PYK2 protein level correlates with the level of TAZ protein in primary breast tumors." (PMID 30250159, 2018). "The large tumor suppressor kinase 1 (LATS1) was down-regulated on both the protein level and on site S48 in breast tumor." (PMID 29109428, 2017). "Thus, an altered mammary microenvironment likely contributes to the dysregulation of LATS1/2 and YAP/TAZ activity in breast tumors." (PMID 36443313, 2022).